BEX1 (brain expressed X-linked 1)
Description:
Signaling adapter molecule involved in p75NTR/NGFR signaling. Plays a role in cell cycle progression and neuronal differentiation. Inhibits neuronal differentiation in response to nerve growth factor (NGF). May act as a link between the cell cycle and neurotrophic factor signaling, possibly by functioning as an upstream modulator of receptor signaling, coordinating biological responses to external signals with internal cellular states (By similarity). In absence of reductive stress, acts as a pseudosubstrate for the CRL2(FEM1B) complex: associates with FEM1B via zinc, thereby preventing association between FEM1B and its substrates (By similarity).
Synonyms: BEX2; HBEX2; HGR74-h
Tractability: PROTAC: UniProt records ubiquitination sites on it; ubiquitination databases record sites on it.
Gene: Protein-coding gene on chromosome X (103,062,645 to 103,064,342, reverse strand). Ensembl gene ENSG00000133169.
Subcellular location: Nucleus; Cytoplasm
Subcellular location (Human Protein Atlas): Cytosol
Gene Ontology:
Molecular function: protein binding; signaling adaptor activity; transcription coactivator binding; molecular function inhibitor activity; signaling receptor binding
Biological process: positive regulation of transcription by RNA polymerase II; negative regulation of protein ubiquitination; signal transduction
Cellular component: transcription regulator complex; cytoplasm; nucleus
Homologues: Orthologues: chimpanzee BEX1 (99% identical), macaque BEX1 (98% identical), pig BEX1 (86% identical), rat Bex2 (77% identical), mouse Bex2 (74% identical), mouse Bex1 (70% identical), rat LOC100912195 (66% identical). Paralogues in human: BEX2 (91% identical), BEX5 (38% identical), BEX3 (32% identical).
Diseases named in the same sentence as BEX1 in open-access papers:
BEX1 is named in the same sentence as 50 diseases in open-access papers, as found by Europe PMC text mining. Sharing a sentence is not in itself a finding about the gene and the disease. The quoted sentences say what the papers report.
glioma (9 papers, 2010 to 2025). A benign or malignant brain and spinal cord tumor that arises from glial cells (astrocytes, oligodendrocytes, ependymal cells). "Mechanism analyses showed LINC00526 functions as a sponge for microRNA-5581-3p (miR-5581-3p) to regulate brain-expressed X-linked 1 (BEX1) expression and, in the end, affects glioma progression." (PMID 33613672, 2021). "Bioinformatic analysis and rescue experiments tool showed that LINC00526 regulates microRNA-5581-3p (miR-5581-3p)/brain-expressed X-linked 1 (BEX1) axis to suppress glioma progression." (PMID 33613672, 2021). "For instance, REST loss in T98G cells led to a reduction in NEDD9 expression, a marker of glioma invasion potential, and an increase in BEX1 expression, a tumor suppressor gene in malignant glioma." (PMID 38609948, 2024). "Collectively, our study indicated LINC00526 serves as a tumor-suppressive lncRNA and directly regulates miR-5581-3p/BEX1 axis in glioma." (PMID 33613672, 2021). "Meanwhile, significant decrease of BEX1 expression was found after miR-5581-3p mimic transfection in glioma cells." (PMID 33613672, 2021). "Next, we explored the effects of BEX1 in regulating glioma cell behaviors." (PMID 33613672, 2021). "Subsequently, BEX1 was confirmed as a target of miR-5581-3p in glioma." (PMID 33613672, 2021). "We showed pBEX1 increased BEX1 expression level in glioma cells." (PMID 33613672, 2021). "In glioma, BEX1 and BEX2 are silenced and the expression could be activated by treatment with DNA methyltransferase inhibitor and histone deacetylase inhibitor." (PMID 27297407, 2016). "In addition, we demonstrated that BEX1 expression was decreased in glioma." (PMID 33613672, 2021). "LINC00526 could inhibit glioma tumor growth by regulating miR-5581-3p/BEX1 axis." (PMID 33613672, 2021). "Furthermore, BEX1 overexpression could inhibit glioma cell growth and invasion." (PMID 33613672, 2021). "We provided evidence that BEX1 expression can be regulated by LINC00526 via sponging miR-5581-3p, which provided new mechanism for low expression status of BEX1 in glioma." (PMID 33613672, 2021). "Of these 8 genes, 6 (SULT4A1, NDRG4, GAP43, BEX1, HINT1, LZTS1) are believed to act as tumor suppressants, while the remaining two, PKM and VIPR1, have been found to be overexpressed in glioma." (PMID 28957313, 2017).
hepatocellular carcinoma (7 papers, 2018 to 2025). A malignant tumor that arises from hepatocytes. "In liver cancer, DNMT1-mediated methylation of BEX1 promoter leads to different stemness of cells in hepatoblastoma (HB) and hepatocellular carcinoma (HCC) and a subtype of HCC with high CSC features (CSC-HCC)." (PMID 36010594, 2022). "Bex1 expression was significantly increased in hepatocellular carcinoma cell lines compared with normal hepatocyte cell lines, promoting cell proliferation." (PMID 29907129, 2018). "The differential expression of BEX1 in tumor and normal tissues is regulated by DNMT1, which maintains the self-renewal capacity of the hepatocellular carcinoma CSCs by activating the Wnt/β-catenin signaling pathway." (PMID 37394582, 2023). "Brain-expressed X-catenin 1 (BEX1) is highly expressed in hepatoblastoma (HB) and the cancer stem cells of hepatocellular carcinoma (CSC-HCC) patients but expressed at low levels in non-CSC-HCC patients." (PMID 37394582, 2023). "BEX1, under the regulation of DNA methyltransferases 1 (DNMT1), was shown to have differential expression levels in Hepatoblastoma, CSC-hepatocellular carcinoma (HCC), and non-CSC HCC patients." (PMID 35659296, 2022).
acute myeloid leukemia (5 papers, 2009 to 2023). Acute myeloid leukemia (AML) is a group of neoplasms arising from precursor cells committed to the myeloid cell-line differentiation. "Deficiency of Bex1 expression led to the decrease of cell proliferation, colony and tumor formation, and the increase of cell apoptosis in acute myeloid leukemia." (PMID 37745297, 2023). "For acute myeloid leukemia (AML) cell lines, a similar correlation exists between MLL translocations and expression of the gene brain expressed X-linked 2 (BEX2, formerly called BEX1)." (PMID 19835597, 2009). "Besides that, BEX1 overexpression could suppress acute myeloid leukemia cell growth and tumor formation." (PMID 33613672, 2021).
heart failure (5 papers, 2017 to 2023). Inability of the heart to pump blood at an adequate rate to meet tissue metabolic requirements. "The expression of the BEX1 gene is linked to heart failure and is associated with gene expression related to heart disease." (PMID 36353510, 2022). "Here, we show that BEX1 is a heart failure-induced gene functioning as an mRNA-associated protein that enhances expression of a subset of cardiac disease-promoting genes." (PMID 29192139, 2017). "Here we discovered that brain-expressed X-linked protein 1 (BEX1) is a novel factor induced during heart failure, which orchestrates inflammatory-signalling through a novel RNA-dependent processing complex." (PMID 29192139, 2017). "One example of an ARE binding protein induced during human heart failure and in a mouse model of TAC induced pressure overload is brain-expressed X-linked protein 1 (BEX1)." (PMID 32164190, 2020). "BEX1 induction during heart failure coincides with increased expression of proinflammatory genes such as tumor necrosis factor-α (TNFα)." (PMID 32164190, 2020). "Here we show that cardiac-specific BEX1 transgenic mice have worse cardiac disease with stress stimulation, while Bex1 gene-deleted mice are protected from heart failure promoting insults." (PMID 29192139, 2017). "Modeling the increase in BEX1 that occurs in disease, cardiac-specific BEX1 transgenic mice show worse cardiac disease with stress stimulation, whereas Bex1 gene-deleted mice are protected from heart failure-promoting insults." (PMID 29192139, 2017). "Here, the authors show that BEX1 is induced during heart failure and is part of a ribonucleoprotein complex enhancing the expression and stability of proinflammatory genes." (PMID 29192139, 2017). "Thus, BEX1 functions as an mRNA-dependent effector that augments pathology-promoting gene expression during heart failure." (PMID 29192139, 2017). "Thus, inhibition of BEX1 protein expression protected the heart from maladaptive remodeling and heart failure following pathologic insults." (PMID 29192139, 2017). "Overall, the absence of BEX1 accelerated CVB3-driven heart failure and pathologic heart remodeling." (PMID 35192678, 2022).
malignant glioma (5 papers, 2008 to 2025). A grade III or grade IV glioma arising from the central nervous system. "Expression of BEX1 increased the sensitivity to chemotherapy-induced apoptosis in malignant glioma and, furthermore, down-regulation of BEX1 in the BCR-ABL positive K562 cell line led to resistance to imatinib treatment." (PMID 26046670, 2015). "A role of BEX1 as a tumor suppressor has previously been suggested in malignant glioma, where BEX1 expression was silenced by extensive promoter hyper-methylation." (PMID 26046670, 2015). "It has more recently been suggested that BEX1 may play a role as a tumour suppressor in malignant glioma." (PMID 18827820, 2008). "BEX1 and BEX2 have also been shown to act as a tumor suppressor in malignant glioma." (PMID 26046670, 2015). "Next generation sequencing of MV4-11 and MOLM-13 cells did not identify any mutations in the BEX1 gene, suggesting that BEX1 expression was probably also down-regulated due to the epigenetic modifications in MV4-11 cells as well as in a group of AML patients similar to in malignant glioma." (PMID 26046670, 2015).
cardiac hypertrophy (3 papers, 2017 to 2025). "Bex1-KO and control mice were thus subjected to TAC surgery, resulting in a phenotype of reduced cardiac hypertrophy after 5 weeks of pressure overload compared with WT controls." (PMID 29192139, 2017). "Similar to what we observed with TAC stimulation, mice lacking the Bex1 gene showed reduced levels of cardiac hypertrophy, no signs of lung congestion and less cardiac fibrosis." (PMID 29192139, 2017).
glioblastoma (3 papers, 2017 to 2023). The most malignant astrocytic tumor (WHO grade IV). "Bex1 and Bex2 have been identified as tumor suppressor genes and are silenced in malignant glioblastoma." (PMID 28145533, 2017). "Re-expression of Bex1 or Bex2 gene by transduction enhanced chemosensitization and apoptosis in glioblastoma cells." (PMID 28145533, 2017). "Current research suggests that in addition to being involved in the regeneration of neuronal axons and regulating the cell cycle, BEX1 is also involved in the proliferation and invasion showed that BEX1 and BEX4 can improve the tumor formation and radio resistance of glioblastoma multiforme cells." (PMID 37745297, 2023).
hepatoblastoma (3 papers, 2023 to 2025). Hepatoblastoma (HB) is a malignant hepatic tumor and is the most common pediatric liver cancer. "Moreover, brain-expressed X-linked protein 1 (BEX1) helps maintain the stem cell-like properties of hepatoblastoma cells by promoting the Warburg effect through a PPARγ/PDK1-dependent pathway." (PMID 39595571, 2024). "In liver hepatoblastoma cells, a recent study demonstrated that spheroid formation was rescued by treatment with the PPAR-γ antagonist GW9662 in BEX1 knockout cells, suggesting that BEX1 promoted the maintenance of hepatoblastoma stemness by inhibiting PPAR-γ." (PMID 41148824, 2025).
liver cancer (3 papers, 2022 to 2023). An epithelial or non-epithelial malignant neoplasm that arises from the liver. "The results of cell viability experiment showed that the viabilities of liver cancer cells decreased significantly after 48 h of BEX1 knockdown compared with the control group." (PMID 37745297, 2023). "Which demonstrated that inhibition of BEX1 suppressed liver cancer cells EMT pathway." (PMID 37745297, 2023). "The DNMT1-mediated methylation of BEX1 regulates stemness and tumorigenicity in liver cancer." (PMID 35795047, 2022).
Alzheimer disease (2 papers, 2020 to 2024). A progressive, neurodegenerative disease characterized by loss of function and death of nerve cells in several areas of the brain leading to loss of cognitive function such as memory and language. "The genes brain expressed X‐Linked 1 (BEX1), brain expressed X‐Linked 3 (BEX3), and Stathmin 1 (STMN1) had been confirmed uniquely down‐regulated in excitatory‐ and inhibitory‐neuron in brain bearing AD according to single‐cell transcriptomic analysis of Alzheimer's disease." (PMID 38923860, 2024). "BEX1 and BEX3 have been recently identified among the most significantly downregulated genes in excitatory neurons of the prefrontal cortex of Alzheimer’s disease patients." (PMID 33100228, 2020).
breast carcinoma (2 papers, 2014 to 2023). "BEX1 is reported to primarily localize to the cytoplasm in all types of cells and to a lesser extent in the nucleus of breast cancer cells." (PMID 24626299, 2014). "Downregulation of BEX1 induces apoptosis and sensitizes breast cancer cells to pro-apoptotic reagents including ceramide and doxorubicin." (PMID 24626299, 2014). "BEX1 is over-expressed in a subset of primary breast cancers and has been shown to prevent breast cancer cells from undergoing apoptosis." (PMID 24626299, 2014). "In breast cancer, overexpression of BEX1 and BEX2 can inhibit the apoptosis of tumor cells." (PMID 37745297, 2023).
cardiomyopathies (2 papers, 2017 to 2022). "Specifically, we adopted genetic gain- and loss-of-function strategies to modulate BEX1 expression in the heart in the context of coxsackievirus B3 (CVB3)-induced cardiomyopathy and found that BEX1 limits viral replication in cardiomyocytes." (PMID 35192678, 2022). "Our results showed that BEX1 expression is induced in the injured heart, and that deleting the Bex1 gene reduced or prevented cardiomyopathy with chronic stress stimulation." (PMID 29192139, 2017). "The progression of these diseases often depends on infiltrating immune cells, and the fact that BEX1 regulates the abundance of myocardial immune cells during injury could suggest that BEX1 is a common regulator of many cardiomyopathies." (PMID 35192678, 2022).
colorectal cancer (2 papers, 2011 to 2019). A primary or metastatic malignant neoplasm that affects the colon or rectum. "Methylation in colorectal cancers ranged from 55% (C3orf14) to 96% (BEX1; median 84%), while methylation in normal tissue was between 0% (CNRIP1, FBN1, INA) and 45% (BEX1; median 5%), P < 0.0001 to P < 0.02." (PMID 21777459, 2011).
hypertrophic cardiomyopathy (2 papers, 2024 to 2025). A condition in which the myocardium is hypertrophied without an obvious cause. "Cardiomyocyte-specific overexpression of Bex1 replicated a hypertrophic cardiomyopathy phenotype, while whole body deletion of Bex1 was protective against pressure overload-induced remodeling." (PMID 38818408, 2024).
viral infection (2 papers, 2022 to 2023). "It should also be noted that Bex1 and 2 were found to be colocalized with the olfactory marker protein in mature olfactory receptor neurons, suggesting a mechanism for loss of smell in the host after viral infection." (PMID 38107402, 2023). "Altogether we discovered BEX1 as a novel determinant of cardiac viral infection that limits viral replication, and that it is a broad antiviral regulator beyond CVB3 and the heart." (PMID 35192678, 2022). "While future work will be needed to further our understanding on the mechanistic insights of BEX1 action in different cell types, our results identify BEX1 as a previously unrecognized player involved in the response to viral infections." (PMID 35192678, 2022). "To test if BEX1 overexpression would protect the heart against viral infection, we then adopted an in vivo model of cardiomyocyte-specific BEX1 overexpression." (PMID 35192678, 2022). "Given the known role of inflammation in both viral clearance and pathogenesis of viral myocarditis, we were prompted to investigate the role of BEX1 in mediating the heart’s response to viral infection." (PMID 35192678, 2022). "Here we report that BEX1 plays a cardioprotective role in the heart during viral infection." (PMID 35192678, 2022). "With this in mind, it is still possible that BEX1 is important in both cardiomyocytes and non-myocyte cell populations in the context of viral infections in vivo." (PMID 35192678, 2022). "In order to determine if BEX1 could protect cells other than cardiac from viral infection, and whether or not BEX1 could protect against viruses other than CVB3, we isolated WT and BEX1 KO mouse embryonic fibroblasts (MEFs) and infected them with three different RNA viruses for 24 hours." (PMID 35192678, 2022).
adenoma (1 paper, 2022). A neoplasm arising from the epithelium. "A previous study reported upregulated BEX1 gene expression in APAs with a CACNA1D or ATP1A1 mutation (that tend to be small adenomas) compared with the larger KCNJ5-mutated APAs." (PMID 36004349, 2022). "The relatively high BEX1 gene expression in smaller versus larger APAs and in aldosterone-producing micronodules (APMs) compared with adjacent zona glomerulosa cells implicates a role for BEX1 in the promotion of cell survival in the initiation of adenoma formation." (PMID 36004349, 2022).
amyotrophic lateral sclerosis (1 paper, 2022). Amyotrophic lateral sclerosis (ALS) is a neurodegenerative disease characterized by progressive muscular paralysis reflecting degeneration of motor neurons in the primary motor cortex, corticospinal tracts, brainstem and spinal cord. "In addition, BEX1 (confers resistance to Amyotrophic Lateral Sclerosis (ALS), was downregulated in the Ala92-Dio2 mice." (PMID 35888752, 2022).
ciliopathy (1 paper, 2022). A genetic disorder of the cellular cilia or the cilia anchoring structures, the basal bodies, or of ciliary function. "Bex1 promotes the formation of primary cilia in both cells and mice, and Bex1 mutations cause ciliopathy phenotypes in mice." (PMID 35144600, 2022). "Loss of Bex1 causes the ciliopathy phenotypes in mice thus linking the Bex1’s molecular property to organogenesis." (PMID 35144600, 2022). "Bex1 knockout mice present ciliopathy phenotypes and exhibit ciliary defects in the retina and striatum." (PMID 35144600, 2022). "Bex1 mutant mice exhibited ciliopathy phenotypes, manifested in the cornea, retina, kidney and cerebellum, forming a constellation of symptoms reminiscent of Joubert syndrome." (PMID 35144600, 2022). "Consistent with this, Bex1 mutant mice displayed ciliopathy phenotypes." (PMID 35144600, 2022). "The sex-dependent variability of the phenotypes may explain why previous research on Bex1 mutant mice did not identify ciliopathy phenotypes." (PMID 35144600, 2022).
Cirrhosis (1 paper, 2019). A chronic disorder of the liver in which liver tissue becomes scarred and is partially replaced by regenerative nodules and fibrotic tissue resulting in loss of liver function. "Human cirrhotic and cirrhosis-associated HCC tissues showed an increase of IMP2 expression and of the progenitor cell markers SOX9, SPP1/osteopontin, CDH1/E-cadherin, AFP, PROM1/CD133, BEX1, EPCAM." (PMID 31555647, 2019).
esophageal squamous cell carcinoma (1 paper, 2021). Esophageal squamous cell carcinoma (ESCC) is a type of esophageal carcinoma (EC) that can affect any part of the esophagus, but is usually located in the upper or middle third. "For example, low BEX1 was identified in esophageal squamous cell cancer and significantly correlated with large tumor size and late tumor stage." (PMID 33613672, 2021).